MTX1 (metaxin 1)
Description:
Involved in transport of proteins into the mitochondrion. Essential for embryonic development (By similarity).
Synonyms: MTX; MTXN
Tractability: Antibody: UniProt predicts a signal peptide or a membrane-spanning region. PROTAC: UniProt records ubiquitination sites on it; ubiquitination databases record sites on it; its protein half-life has been measured.
Gene: Protein-coding gene on chromosome 1 (155,208,695 to 155,213,824, forward strand). Ensembl gene ENSG00000173171.
Subcellular location: Membrane; Mitochondrion outer membrane
Subcellular location (Human Protein Atlas): Mitochondria
Pathways (Reactome):
Organelle biogenesis and maintenance: Cristae formation
Protein localization: Mitochondrial protein import
Signal Transduction: RAC2 GTPase cycle
Gene Ontology:
Molecular function: protein binding
Biological process: inner mitochondrial membrane organization; mitochondrial outer membrane translocase complex assembly; protein insertion into mitochondrial outer membrane; lactation
Cellular component: MIB complex; mitochondrion; SAM complex; membrane; mitochondrial outer membrane
Genetic constraint (gnomAD): Loss-of-function variants: 20 observed, 32.34 expected, observed/expected ratio (o/e) 0.62, 90% interval 0.43 to 0.9. The upper end of that interval is the gene's LOEUF score, 0.9, which puts it in group 3 of 6, group 1 being the genes least tolerant of losing a copy. Missense variants: 463 observed, 397.84 expected, observed/expected ratio (o/e) 1.16, 90% interval 1.08 to 1.26. Synonymous variants: 196 observed, 159.72 expected, observed/expected ratio (o/e) 1.23, 90% interval 1.09 to 1.38.
Homologues: Orthologues: macaque MTX1 (95% identical), rabbit MTX1 (86% identical), pig MTX1 (80% identical), mouse Mtx1 (77% identical), chimpanzee MTX1 (75% identical), rat Mtx1 (73% identical), dog MTX1 (63% identical), zebrafish mtx1b (42% identical), zebrafish mtx1a (40% identical), tropical clawed frog mtx1 (24% identical), Caenorhabditis elegans mtx-1 (22% identical), Drosophila melanogaster CG9393 (21% identical). Paralogues in human: MTX3 (31% identical), FAXC (18% identical), MTX2 (17% identical).
Diseases named in the same sentence as MTX1 in open-access papers:
MTX1 is named in the same sentence as 19 diseases in open-access papers, as found by Europe PMC text mining. Sharing a sentence is not in itself a finding about the gene and the disease. The quoted sentences say what the papers report.
gout (3 papers, 2022 to 2024). A condition characterized by painful swelling of the joints, which is caused by deposition of urate crystals. "Moreover, rs9286836 (NUDT17) and rs4971100 (TRIM46), rs4072037 (MUC1) and rs2974935 (MTX1) also revealed significant associations with gout (all p-values <1e−8)." (PMID 36221101, 2022). "Surprisingly, variants on chromosome 1, such as rs7546668 (DNAJC16), rs10927807 (AGMAT), rs9286836 (NUDT17), rs4971100 (TRIM46), rs4072037 (MUC1), and rs2974935 (MTX1), showed significant associations with gout in both discovery and replication cohorts (all p-values < 1e−8)." (PMID 36221101, 2022). "This study identified 17 genetic loci associated with gout, including four genes related by protein-protein interaction network (PPI) analysis: TRIM46, THBS3, MTX1 and KRTCAP2." (PMID 38831441, 2024). "We identified 17 association signals for gout at unique genetic loci, including four genes related by protein-protein interaction network (PPI) analysis: TRIM46, THBS3, MTX1, and KRTCAP2." (PMID 38831441, 2024). "Three LD blocks existed in chromosome 1 for the variants relating to gout, which were composed of genes DNAJC16, AGMAT (first block), PDZK1, CD160, NUDT17 (second block), TRIM46, MUC1, MTX1, and ASH1L (third block)." (PMID 36221101, 2022). "This study performed a GWAS in a large sample size and found genes DNAJC16, AGMAT, NUDT17, TRIM46 MUC1, and MTX1 on chromosome 1 relating to gout disease." (PMID 36221101, 2022). "Surprisingly, variants on chromosome 1 located in genes DNAJC16, AGMAT, NUDT17, TRIM46, MUC1 and MTX1 showed significant associations with gout, which finding had not been reported before." (PMID 36221101, 2022).
Parkinson disease (3 papers, 2015 to 2024). A progressive degenerative disorder of the central nervous system characterized by loss of dopamine producing neurons in the substantia nigra and the presence of Lewy bodies in the substantia nigra and locus coeruleus. "Mutations in MTX1 have also been linked to Parkinson’s disease." (PMID 25886137, 2015).
hepatocellular carcinoma (2 papers, 2021 to 2025). A malignant tumor that arises from hepatocytes. "MTX1 mediates autophagy, leading to sorafenib resistance in hepatocellular carcinoma cells or participating in aging." (PMID 41498025, 2025).
breast carcinoma (1 paper, 2023). "Interestingly, we found a robust causal association (OR per SD, 1.17; 95% CI: 1.12–1.23, PSMR = 1.85 × 10−8) between MTX1 expression and luminal A-like breast cancer, specifically." (PMID 36634566, 2023).
cholangiocarcinoma (1 paper, 2025). A carcinoma that arises from the intrahepatic biliary tree (intrahepatic cholangiocarcinoma) or from the junction, or adjacent to the junction, of the right and left hepatic ducts (hilar cholangiocarcinoma). "Cell test results revealed MTX1 expression was considerably greater in cholangiocarcinoma cells than HIBEpic cells (p < 0.001)." (PMID 41498025, 2025). "Based on the UALCAN analysis, we found that NKILA, MTX1, and TOMM40 were highly expressed in cholangiocarcinoma." (PMID 41498025, 2025).
chronic kidney disease (1 paper, 2021). Impairment of the renal function secondary to chronic kidney damage persisting for three or more months. "Both THBS3 and MTX1 were tubular-specifically expressed, and the expressions were greatly downregulated in chronic kidney disease." (PMID 33627123, 2021).
COVID-19 (1 paper, 2024). A disease caused by infection with severe acute respiratory syndrome coronavirus 2. "Our comprehensive analysis revealed that four common genes, B4GALNT2, MTX1, POLR2J, and TUBB4B are differentially expressed in patients with both COVID-19 and diabetic peripheral neuropathy." (PMID 38957825, 2024).
epilepsy (1 paper, 2025). A brain disorder characterized by episodes of abnormally increased neuronal discharge resulting in transient episodes of sensory or motor neurological dysfunction, or psychic dysfunction. "We found that CDC25B, DNMT1, GZMA, MTX1, and SSH2 expression decreases epilepsy risk, whereas FGD3, RAF1, and SH3BP5L increase it." (PMID 39753851, 2025).
gastric cancer (1 paper, 2021). A primary or metastatic malignant neoplasm involving the stomach. "In addition, genome-wide association studies (GWASs) have reported that MTX1 is one of the high-quality biomarkers of gastric cancer susceptibility 16, implicating the key role of MTX1 in promoting cancer progression." (PMID 34421355, 2021).
glioblastoma (1 paper, 2022). The most malignant astrocytic tumor (WHO grade IV). "In resting glioblastoma cells, Bak was identified as part of three complexes involving proteins from the mitochondrial importation/sorting machinery—namely, VDAC2/Mtx1/Mtx2/Bak, Mtx1/Mtx2/Bak, and Mcl-1/TOM70/Mtx2/Bak." (PMID 35204663, 2022).
steatosis (1 paper, 2021). Increased lipid within the cytoplasm of cells. "For the “oxidative stress” pathway, two genes (NFκB1 and MTX1) were lower in steatosis compared to HOC." (PMID 34869521, 2021).
cancer (3 papers, 2006 to 2025). A tumor composed of atypical neoplastic, often pleomorphic cells that invade other tissues. "MTX1, a mitochondrial protein, may be implicated in the Warburg process, a metabolic characteristic of cancers." (PMID 41498025, 2025). "This is the first time to report the function of MTX1 in cancer development and drug resistance to date." (PMID 34421355, 2021). "Accordingly, we hypothesized that NKILA may promote Warburg effect in cancers via upregulating MTX1 and enhancing its interaction with TOMM40." (PMID 41498025, 2025). "Our further explorations indicated that MTX1 interacts with CISD1 by Co-IP assays, whereas CISD1 functions as an autophagy repressor in cancer." (PMID 34421355, 2021). "Three corresponded to genetic determinants of genetic syndromes (MTMR, DISC1, MTX1) and the three others bore functions with no obvious link to cancer (NENF, ENSA, TARBP1)." (PMID 17060936, 2006).
infection (2 papers, 2022 to 2025). The state of being infected such as from the introduction of a foreign agent such as serum, vaccine, antigenic substance or organism. "Theses toxins are structurally and mechanistically distinct from MTX1 toxins found in toxigenic P. larvae strains that result in infection of honeybee larvae." (PMID 40858718, 2025).
tumor (2 papers, 2021 to 2025). "Next, we constructed a mouse ICC model using HuCCT1 or RBE cells and found that NKILA silencing inhibited tumor growth compared to KD‐NC + OE‐NC, which was reversed by MTX1 overexpression (p < 0.05)." (PMID 41498025, 2025). "The final data clearly demonstrated that overexpression of MTX1 not only enhanced tumor formation ability, but also conferred resistance of HCC cells to sorafenib." (PMID 34421355, 2021). "In addition, through rescue experiments, we demonstrated that MTX1 overexpression reversed NKILA silencing‐suppressed tumor growth, cell viability, EMT, and Warburg effect, and NKILA silencing‐enhanced apoptosis and autophagy." (PMID 41498025, 2025). "In addition, our qRT-PCR data confirmed the upregulation of MTX1 in HCC tumor tissues from our hospital." (PMID 34421355, 2021). "Clinical sample validation showed that MTX1 and TOMM40 expressions were higher in tumor tissues than adjacent tissues (p < 0.01)." (PMID 41498025, 2025). "The staining results showed that MTX1 expression was high in 48.8%, weak in 30%, and negative in 21.2% of tumor cases according to the standard mentioned in methods section." (PMID 34421355, 2021).
MTX1 also shares sentences with these, for which no sentence is quoted: blood disease (1 paper); hematological disorders (1); hyperuricemia (1); mandibuloacral dysplasia progeroid syndrome (1); Parkinson (1).